TMEM106B (transmembrane protein 106B)
Diseases named in the same sentence as TMEM106B in open-access papers (continued):
Sharing a sentence is not in itself a finding about the gene and the disease.
neurodegenerative disease (continued). "Further, expression of TMEM CT in C. elegans neurons provides a useful model for the functional characterization of TMEM106B proteinopathy in neurodegenerative disease." (PMID 38915598, 2024). "A new amyloid fibril composed of a C-terminal fragment of TMEM106B was found in many Neurodegenerative diseases and normal elderly." (PMID 38710967, 2024). "Transmembrane protein 106B (TMEM106B), a protein that is localized to the lysosome, is genetically linked to many neurodegenerative diseases and forms fibrils in diseased brains." (PMID 37545650, 2023). "Recent new studies reported that TMEM106B proteins form intracellular amyloid filaments which universally exist in various neurodegenerative diseases, sometimes being the dominant form of protein aggregation." (PMID 37563705, 2023). "Given that TMEM106B is intimately linked to brain aging, myelination disorder, and a vast number of neurodegenerative diseases, future research is warranted to fully elucidate TMEM106B functions in these different brain cell types." (PMID 37146150, 2023). "Several recent studies have reported that a cleaved C-terminal fragment of TMEM106B forms amyloid fibrils with ageing and in neurodegenerative diseases." (PMID 37726834, 2023). "In light of the recent findings that TMEM106B can form protein aggregates commonly seen in patients with neurodegenerative diseases, we here propose a model that reconciles the phenotype of TMEM106B deficiency and overexpression." (PMID 37563705, 2023). "In this review, we propose a novel mechanism for neurodegenerative diseases inspired by the widely identification of TMEM106B deposition." (PMID 37563705, 2023). "More intriguingly, the C-terminal fragment of TMEM106B was recently found to form amyloid fibrils in the aged brain and several neurodegenerative diseases." (PMID 37146150, 2023). "In agreement with our findings, recent studies have shown age-dependent TMEM106B fibril accumulation in the frontal cortex of mixed cohorts with multiple neurodegenerative diseases." (PMID 37726834, 2023). "Over the past months, several research groups have reported the cryo-EM structures of TMEM106B filaments derived from the brains of a variety of neurodegenerative diseases as well as older neurologically normal individuals." (PMID 36056242, 2022). "Very recently, TMEM106B amyloid filaments were discovered in the brains of older patients with various neurodegenerative diseases, including tauopathies, synucleinopathies, Aβ-amyloidoses and TDP-43 proteinopathies." (PMID 36003149, 2022). "The recognition that TMEM106B can form amyloid fibrils and is present across neurodegenerative diseases sheds new light on TMEM106B as a central player in neurodegeneration and brain health, but also raises important new questions." (PMID 36056242, 2022). "Meanwhile, these findings highlight the importance to better understand TMEM106B function and dysfunction in the context of normal aging and neurodegenerative diseases." (PMID 33461566, 2021). "Taken together, these results provide novel insights into the role of PGRN and TMEM106B in brain aging and neurodegenerative diseases." (PMID 32852886, 2020). "Although GRN and TMEM106B were initially identified as genes associated with FTLD, these two genes have been intimately linked to brain health and associated with many other neurodegenerative diseases." (PMID 32852886, 2020). "Given the clear protective effect of TMEM106B SNPs against multiple FTD subtypes and the emerging role of TMEM106B in aging and other neurodegenerative diseases, further study of TMEM106B’s effects in the brain are an important area for future research." (PMID 29929528, 2018). "TMEM106B was initially identified as a risk factor for FTLD, but recent studies highlighted its general role in neurodegenerative diseases." (PMID 30332472, 2018).
neurodegenerative disease (continued). "The broad involvement of TMEM106B in neurodegenerative diseases makes it an important gene to characterize and a promising target for potential therapies." (PMID 29970152, 2018). "All of these observations suggest that TMEM106B plays a key role in the pathology not only of FTLD-TDP but also of other neurodegenerative diseases, such as AD." (PMID 24684749, 2014). "Recent studies indicate that TMEM106B plays a pathological role in a wide range of neurodegenerative diseases." (PMID 24684749, 2014). "The lysosomal transmembrane protein 106B (TMEM106B) forms amyloid filaments in the human brain in an age-dependent manner, observed both in neurologically healthy individuals and in patients with neurodegenerative diseases also containing tau, α-synuclein, or TDP-43 inclusions." (PMID 41570984, 2026). "Finally, we consider future directions for PGRN and TMEM106B research designed to develop novel therapies targeting common mechanisms of multiple neurodegenerative diseases." (PMID 40713630, 2025). "Importantly, recent discoveries of TMEM106B amyloid fibrils in varied neurodegenerative diseases and glycosphingolipid regulation by progranulin and TMEM106B further support their central roles in cross-disease neurodegenerative mechanisms." (PMID 40713630, 2025). "As such, knock-out of Tmem106b does not model the changes downstream of the genetic variation on the risk haplotype observed in neurodegenerative diseases and aging." (PMID 40269985, 2025). "Second, as TMEM106B fibrils have been found in various Neurodegenerative diseases, it needs to be clarified whether TMEM106B fibrils have synergistic or antagonistic effects on promoting aggregation of pathological proteins in Neurodegenerative diseases." (PMID 38710967, 2024). "Furthermore, TMEM106B has been investigated as a disease modifier in the context of healthy aging and across multiple neurodegenerative diseases." (PMID 39321401, 2024). "Aberrant TMEM106B expression and deposition were detected in neurodegenerative diseases." (PMID 38710967, 2024). "Given that TMEM106B plays an important role in the pathological progression of Neurodegenerative diseases, TMEM106B may be used as a therapeutic target." (PMID 38710967, 2024). "Finally, we summarized the identification and cryo-electronic microscopic structure of TMEM106B fibrils, and discussed the promising therapeutic strategies aimed at TMEM106B fibrils and the future directions for TMEM106B research in neurodegenerative diseases." (PMID 38710967, 2024). "Also, different methods should be conducted to verify the amyloid protein properties of TMEM106B in various Neurodegenerative diseases." (PMID 38710967, 2024). "Several studies identified that TMEM106B may play a role in the pathogenesis of neurodegenerative diseases." (PMID 38710967, 2024). "Although its exact role in the pathogenesis of neurodegenerative diseases remains unclear, studies have shown that TMEM106B appears to affect the pathological burden of TAR DNA binding protein-43 (TDP-43) pathology." (PMID 38710967, 2024). "In addition, in patients with neurodegenerative diseases, the amount of TMEM106B fibrils are found to be higher than age-matched control brains." (PMID 37563705, 2023). "A deeper understanding of the risk- and disease-modifying effect of TMEM106B will be essential and could hold the key towards new insights and therapeutic avenues for FTD and related neurodegenerative diseases." (PMID 37077569, 2023). "TMEM106B mutations could lead to lysosome dysfunction by promoting the aggregation of TMEM106B and reducing these aggregations may restore lysosomal function, providing a potential therapeutic target for various neurodegenerative diseases." (PMID 37563705, 2023). "In addition to GRN and TMEM106B, many other lysosomal genes are directly involved in neurodegenerative diseases and lysosomal dysfunction has emerged as a common mechanism for neurodegeneration." (PMID 32852886, 2020).
neurodegenerative disease (continued). "Variation in transmembrane protein 106B (TMEM106B) has been associated with enhanced neuroinflammation during aging and with TDP-43-related neurodegenerative disease, and rs3173615, a missense coding SNP in TMEM106B, has been implicated as a functional variant in these processes." (PMID 30390709, 2018). "Additionally, variation in TMEM106B is associated with TDP-43 pathology, a feature found in many cases of CTE, as well as several other neurodegenerative diseases." (PMID 30390709, 2018). "Thus, PGRN and TMEM106B may play a central role in common pathological mechanisms shared across various neurodegenerative diseases, enhancing their potential impact as therapeutic targets with broad application." (PMID 40713630, 2025). "However, the precise mechanism of TMEM106B at the lysosomal membrane is undetermined and it remains unknown how TMEM106B contributes to the development of Neurodegenerative diseases." (PMID 38710967, 2024). "Yet, the precise mechanism of TMEM106B in Neurodegenerative diseases remains unclear." (PMID 38710967, 2024). "However, given that TMEM106B aggregation occurs in multiple neurodegenerative diseases as well as in general aging, whether TMEM106B C-terminal aggregates correlate with TDP-43 pathology specifically in ALS is unclear." (PMID 39606446, 2024). "Thus, it is possible that increasing levels of TMEM106B might be contributing to the higher risks for developing neurodegenerative diseases." (PMID 37563705, 2023). "Of interest is the detection of up-regulation of Tmem106b, a lysosomal/endosomal protein that has been of great interest lately, as it has been shown to form amyloid filaments in the aged human brain and, in a similar manner, in different neurodegenerative diseases." (PMID 37174641, 2023). "Li and colleagues conducted a stratification analysis and found that TMEM106B rs1990621 variant could regulate the neuronal proportion in AD cases, other neurodegenerative diseases, elderly cognitively healthy controls, but not young controls." (PMID 33461566, 2021). "Importantly, however, results from these knock-out models merely underlined the tight regulation and importance of adequate levels of TMEM106B in the brain, and did not model the changes downstream of the risk haplotype observed in human neurodegenerative diseases and aging." (PMID 40269985, 2025). "Accumulation of TMEM106B fibrils composed of cleaved C-terminal fragments (CTF) of transmembrane protein 106B (TMEM106B) has recently been observed in the brains of elderly subjects and individuals with neurodegenerative diseases." (PMID 37937069, 2023). "The elucidation of TMEM106B fibrils in FTLD-TDP-derived samples recalls for deeper analysis of the role of TDP-43 in this pathology and TMEM106B in other neurodegenerative diseases." (PMID 37895336, 2023). "In this study, we have provided an initial characterization of TMEM106B protein expression in normal, GRN (−) FTLD-TDP, and GRN (+) FTLD-TDP human brain, as well as other neurodegenerative disease controls." (PMID 24252750, 2013). "First, TMEM106B fibrils are present in older adults without neurodegenerative disease, and their pathogenicity needs to be further determined." (PMID 38710967, 2024). "TMEM106B filaments were previously shown to accumulate in neurologically normal brains, as well as in the presence of neurodegenerative disease-characteristic amyloid filaments, with no clear relationship between disease status and TMEM106B filament fold." (PMID 38057661, 2024). "Unlike many neurodegenerative disease-related proteins, TMEM106B does not form pathological inclusions in diseased brain." (PMID 24252750, 2013). "Furthermore, the SNP is localized within a recently discovered 135 amino acid filament that originates from the C terminus of the TMEM106B protein which is common to neurodegenerative diseases characterized by tau, TDP-43, and α-synuclein." (PMID 41264095, 2025).
neurodegenerative disease (continued). "Since little is known about TMEM106B and its expression in human brain, we performed immunohistochemical studies of TMEM106B in postmortem human brain samples from normal individuals, FTLD-TDP individuals with and without GRN mutations, and individuals with other neurodegenerative diseases." (PMID 24252750, 2013). "To corroborate this finding, we also extracted TMEM106B fibrils from two other brain tissues, one from case 2 of PDD patient and the other from case 6 of non-neurodegenerative disease (non-ND) control, corresponding to PDD case and normal 2 case in our previously study, respectively." (PMID 39872397, 2024).
brain disorder (7 papers, 2019 to 2025). A disease affecting the brain or part of the brain. "It is likely that the decreased expression or deficiency of TMEM106B is linked to some brain diseases." (PMID 39194695, 2024). "Transmembrane protein 106B (TMEM106B) has been linked to many brain disorders and brain aging." (PMID 40451428, 2025). "TMEM106B has been closely associated with brain aging and many brain disorders." (PMID 37146150, 2023). "TMEM106B has been associated with brain aging and many brain disorders." (PMID 35287730, 2022). "TMEM106B is intimately linked with brain aging and brain disorders." (PMID 35287730, 2022). "Thus, the effect of TMEM106B in the cerebellum might influence cognitive, executive, and emotional functions during brain aging and the progression of TMEM106B-associated brain disorders." (PMID 35287730, 2022). "Recent studies on brain diseases illustrate the role of the TMEM106B protein in regulating many aspects of lysosomal function." (PMID 39194695, 2024). "In this study, we investigate the role of TMEM106B in the cerebellum, dysfunction of which has been associated with FTLD and other brain disorders." (PMID 35287730, 2022). "This processing might be relevant to the recent findings that aggregates composed of the C-terminal fragment of TMEM106B accumulate in elderly patients with brain disorders." (PMID 40451428, 2025). "Additionally, investigating the impact of TMEM106B variants and the formation of TMEM106B C-terminal amyloid fibrils on TMEM106B function will be critical for understanding how TMEM106B regulates brain aging and brain disorders." (PMID 37146150, 2023). "Moreover, TMEM106B’s risk-modifying capabilities go beyond disease protection alone, as it has been linked to brain aging even in the absence of known brain disease." (PMID 36056242, 2022). "Given that neurodegeneration and brain diseases are complex disorders with several contributing factors, there might not be one answer to explain the role of TMEM106B fibrils in all implicated disorders." (PMID 36056242, 2022).
infection (6 papers, 2014 to 2025). The state of being infected such as from the introduction of a foreign agent such as serum, vaccine, antigenic substance or organism. "This amino acid change, occurring in six cell lines except Calu-3, can promote SARS-CoV-2's infection in ACE2-negative cells via the TMEM106B pathway." (PMID 41147188, 2025). "Combined, these two substitutions abrogated S1 binding in vitro and the ability of TMEM106B to support infection with SARS-CoV-2 Belgium/GHB-03021/2020 and VOC omicron, without affecting correct TMEM106B expression and localization." (PMID 37421949, 2023). "To confirm that TMEM106B can support ACE2-independent infection, we generated ACE2 and TMEM106B knockout NCI-H1975 cells (ACE2KO and TMEM106BKO)." (PMID 37421949, 2023). "TMEM106B overexpression in Huh7 cells enhanced infection with all isolates, whereas infection with the TMEM106B-independent coronavirus HCoV-229E remained unaffected." (PMID 37421949, 2023). "As expected, ACE2 knockout did not prevent cytopathic effect (CPE) induction or viral RNA production by SARS-CoV-2, whereas TMEM106B knockout completely abolished infection." (PMID 37421949, 2023). "Our data also show that multiple SARS-CoV-2 isolates can use TMEM106B for infection, but mechanistic studies were mainly performed using a SARS-CoV-2 isolate that contains spike substitution E484D." (PMID 37421949, 2023). "We showed that TMEM106B overexpression enhanced infection by pseudoviruses carrying SARS-CoV-2 spike." (PMID 37421949, 2023). "Several studies reported the infection of ACE2-negative cells, and here we show that SARS-CoV-2 can enter ACE2-deficient host cells via a TMEM106B-dependent entry mechanism." (PMID 37421949, 2023). "We previously reported that TMEM106B is essential for the infection of several human cell lines that express ACE2 at a low or an undetectable level, including Huh7 and lung-derived NCI-H1975 cells." (PMID 37421949, 2023). "We previously showed that SARS-CoV-2 can use TMEM106B for the infection of several airway-derived cell types." (PMID 37421949, 2023). "Knockout of EXT1, a gene essential for heparan sulfate synthesis, also inhibited SARS-CoV-2 infection via ACE2 and TMEM106B, confirming the supporting role of heparan sulfate for both infection routes." (PMID 37421949, 2023). "Within the locus we also identified host genes whose expression increased (Samd9l, Asns, Gpr85, and Tfpi2) or decreased (Pon1, Hepacam2, Tmem106b, and Pppr9a1) 2-fold (P < 0.05) 72 hours after infection with H5N1 IAV in D2, B6 or both mouse strains." (PMID 25418976, 2014). "It is hypothesized that TMEM106B dysregulation may similarly limit intracellular pathogen clearance during OM, thereby exacerbating infection spread and bone tissue destruction." (PMID 41050653, 2025). "TMEM106B-mediated infection is also enhanced by heparan sulfate." (PMID 37421949, 2023). "Pretreatment of SARS-CoV-2 with heparan sulfate or the structurally similar glycosaminoglycan heparin inhibited the infection of NCI-H1975 cells via the ACE2- as well as the TMEM106B-dependent route, confirming the capacity of SARS-CoV-2 to bind glycosaminoglycans." (PMID 37421949, 2023). "Moreover, blocking that surface pool with anti-TMEM106B antibodies concurrently with virus addition was sufficient to prevent infection." (PMID 37421949, 2023). "Intriguingly, compared to other host receptors of SARS-CoV-2, such as ACE2, ASGR1, KREMEN1, and TMEM106B exhibits broader and higher expression levels in both cell lines and tissues, implying that TMEM106B may facilitate the infection of ACE2-negative cells in diverse tissues." (PMID 41147188, 2025). "Moreover, TMEM106B overexpression in Huh7 ACE2KO cells stimulated infection." (PMID 37421949, 2023). "This suggests that, despite the importance of TMEM106B, ACE2, and heparan sulfate for infection, SARS-CoV-2 can still attach to the cell surface via additional factors, possibly via sialylated glycans." (PMID 37421949, 2023).
infection (continued). "Here, we show that TMEM106B and ACE2 can support separate infection mechanisms." (PMID 37421949, 2023). "The observation that TMEM106B supports the infection of ACE2-negative cells suggests that TMEM106B can function as an autonomous receptor, rather than a cofactor for ACE2." (PMID 37421949, 2023). "TMEM106B knockout in NCI-H1975 cells reduced viral RNA production by the SARS-CoV-2 isolates, but not HCoV-229E, demonstrating that different SARS-CoV-2 isolates depend on TMEM106B for infection." (PMID 37421949, 2023). "It, therefore, remains to be fully established whether TMEM106B-dependent infection by SARS-CoV-2 isolates lacking the E484D substitution involves the same mechanism." (PMID 37421949, 2023). "Although we show that TMEM106B is essential for SARS-CoV-2 infection only in cells lacking high-level ACE2 expression, we speculate that TMEM106B might also play a role in ACE2-mediated infection." (PMID 37421949, 2023). "However, viruses lacking this residue can also employ TMEM106B for infection." (PMID 37421949, 2023). "As SARS-CoV-2 has been found to replicate in many organs, including organs that express ACE2 at low levels, such as the brain, we tested whether SARS-CoV-2 can use TMEM106B for the infection of several non-airway cell types derived from the intestines and brain." (PMID 37421949, 2023).